CLU (clusterin)
Diseases named in the same sentence as CLU in open-access papers (continued):
Sharing a sentence is not in itself a finding about the gene and the disease.
Alzheimer disease (continued). "A recent convergence of genome-wide association studies and the peripheral measurement of circulating levels of acute phase proteins have focused attention on Clusterin as a modifier of late-stage Alzheimer disease and a biomarker for advanced neurodegeneration." (PMID 24366862, 2014). "The predicted target gene of miR-16-5p was CLU that could clear of beta amyloid peptide, which was one of the major brain lesions with Alzheimer’s disease." (PMID 25231540, 2014). "Moreover, a recent study has shown that increased plasma clusterin concentrations are significantly related to the severity and progression of Alzheimer's disease, suggesting that plasma clusterin as a potential peripheral biomarker of Alzheimer's disease." (PMID 25076422, 2014). "Besides clusterin, various inflammatory proteins and cytokine levels are increased in the blood and cerebrospinal fluid of Alzheimer's disease patients." (PMID 25076422, 2014). "Since Alzheimer's disease is more prevalent in subjects with middle-aged obesity and insulin resistance, we investigated the relationship between the plasma clusterin levels and the parameters of adiposity, metabolic syndrome, and systemic inflammation in healthy Korean subjects." (PMID 25076422, 2014). "Proteins expressed by HSV-1 are homologous to all of the protein products of the major susceptibility gene in Alzheimer's disease (APOE, clusterin, complement receptor 1, and PICALM) as well as to APP and tau and over 100 others implicated in genetic association studies." (PMID 21234306, 2010). "Recent sequencing data from human Alzheimer’s disease patients and healthy controls demonstrated that healthy controls have three subpopulations of OPCs, and that one of these populations expressed high levels of Clusterin, one of the genes we identified as significantly upregulated in OPC158." (PMID 35902669, 2022). "Genetic studies including genome-wide studies have also associated inflammation-related genes to the etiology of Alzheimer’s disease (i.e. ABCA7, CLU, CR1, HLA-DRB1, HLA-DRB5, PICALM, and TREM2), further supporting the concept of neuroinflammation as a pathogenic factor in Alzheimer’s disease." (PMID 34335238, 2021). "Lipoprotein clearance may play an important role in Alzheimer’s disease pathogenesis through the association of APOE and several other genes that function in lipid or lipoprotein metabolism, including Clusterin (CLU) and ATP binding cassette (ABC) transporter A7 (ABCA7,)." (PMID 32299494, 2020). "The present data concludes that the major T allele of CLU rs9331896 is associated with a high risk of Alzheimer’s disease and all dementia, but not with atherosclerosis-related diseases like vascular dementia, ischemic cerebrovascular disease, and ischemic heart disease." (PMID 29534716, 2018). "On the other hand, UCHL1 and clusterin have been described as important enhancers of neuroprotection and neurogenesis (e.g., neuronal process formation, elongation, and plasticity) as well as a potential target into some neurodegenerative disorders such as Alzheimer’s disease." (PMID 26204925, 2015). "Higher levels of clusterin in the synapsis of APOE4 carriers contribute to synapse degeneration and synaptic accumulation of toxic amyloid beta in Alzheimer’s disease." (PMID 37240249, 2023). "The second study also identified CLU as well as CR1 in a total discovery and replication sample of 14,636 subjects (6010 cases, 8625 controls) from the European Alzheimer’s Disease Initiative (EADI)." (PMID 34935119, 2022). "Clusterin (CLU), a molecular chaperone, was consistently found to interfere with Aβ aggregation in Alzheimer’s Disease (AD)." (PMID 33003328, 2020). "Our results strongly suggest the active roles of C7, together with other complement components such as the GWAS hits CR1, CLU and CFH, in the development of Alzheimer's disease." (PMID 31032141, 2019).
Alzheimer disease (continued). "For example, the glycosylation of clusterin regulates the neurotoxicity of amyloid-beta peptides in Alzheimer’s disease where non-glycosylated clusterin can provide a partial protection." (PMID 36768261, 2023). "Apart from the “Total 17 NAbs” cluster, the NAb clusters for “Alzheimer’s disease” (SORL1, ADAM10, CLU and TREM2) and “Neurodegenerative disease” (SORL1, ADAM10, CLU and TREM2 and WWOX) showed the best diagnostic performance for AD with sensitivity (against 95% specificity) up to 0.759." (PMID 36922858, 2023). "Clusterin has been indicated as a potential plasma or cerebrospinal fluid (CSF) biomarker of both PD and Alzheimer’s disease (AD), however, with controversial and non-reproducible results." (PMID 32266064, 2020). "This indicates that an APOE4 genotype increases the amount of clusterin at remaining synapses in Alzheimer's disease but not overall in the temporal cortex." (PMID 31853523, 2019). "But other studies have shown that plasma clusterin levels were not related to Alzheimer’s disease or presymptomatic AD." (PMID 27861589, 2016). "This method will enable researchers to carry out genetic polymorphism studies for genetic risk factors associated with late-onset Alzheimer’s disease (BIN1, CLU, ABCA7, CR1 and PICALM) without the use of expensive instrumentation and reagents." (PMID 23419238, 2013). "To achieve this, we isolated synaptoneurosomes from post-mortem tissue of Alzheimer's disease and non-demented control individuals of known APOE genotypes which were then probed for clusterin levels." (PMID 31853523, 2019). "Interestingly, clusterin has also been shown to prevent LDL oxidation by arterial wall cells, suggesting that clusterin may play anti-atherogenic as well as anti-amyloidogenic roles, creating the rationale for investigating both atherosclerosis-related diseases and Alzheimer’s disease." (PMID 29534716, 2018).
prostate carcinoma (75 papers, 2004 to 2026). A carcinoma that arises from epithelial cells of the prostate gland. "Although secreted clusterin (sCLU) is commonly overexpressed in colon carcinoma, reduced levels of sCLU have been associated with poor prognoses in prostate cancers." (PMID 40671119, 2025). "In fact, many studies have reported findings related to the association between CLU expression and cancer incidence and progression, such as in lung cancer, prostate cancer, colon cancer, and hepatocellular carcinoma." (PMID 37239129, 2023). "In malignant prostatic neoplasms, androgen ablation led to significantly elevated levels of clusterin underlining its role in therapeutic resistance and generalized protection of PCa cells." (PMID 31426412, 2019). "Clusterin has been associated with impaired apoptosis in prostate cancer cells via interaction with activated Bax22." (PMID 29382921, 2018). "Clusterin(CLU), also known as apolipoprotein J, is a 75–80 kDa disulfide-linked heterodimeric protein, overexpressing in many cancers such as prostate cancer, lung cancer, breast cancer, etc.." (PMID 28954633, 2017). "Under cell stress, such as treatment with trastuzamab in breast cancer cells, or following androgen ablation in prostate cancer cells, significant increase in CLU expression was associated with activation of alternative signaling." (PMID 22417809, 2012). "Clusterin is encoded by a single gene located on chromosome 8p21–p12, a locus commonly deleted in early stage prostate cancer." (PMID 15494717, 2004). "This androgen regulation of CLU may underline the cytoprotective role of androgens in normal prostate physiology as well as an anti-apoptotic function in prostate cancer progression." (PMID 37685987, 2023). "It has been shown that antisense mutations in the CLU gene, resulting in the silencing of gene expression, may increase the chemosensitivity of prostate cancer cells, which is probably caused by blocking the antiapoptotic properties of clusterin." (PMID 36071866, 2022). "Taken together, the reduction in HSP27, CFLIP, and CLU expression by doxazosin inhibits Bcl-2 function and thereby induces apoptosis in prostate cancer cells." (PMID 38535120, 2024). "CLU acts as a downstream mediator of TGF-beta in prostate cancer, which is activated by Twist1 (transcription factor)." (PMID 39253532, 2024). "In prostate cancer cells, the Twist transcription factor binds to the E-box in the CLU gene and mediates TGFβ-induced CLU expression." (PMID 39253532, 2024). "Our study shows that the administration of doxazosin after a single knockdown of the HSP27, cFLIP, and CLU genes in PC-3 cells, a prostate cancer cell line, leads to increased apoptosis." (PMID 38535120, 2024). "For instance, miRNA-217-5p and miRNA-195 have been found to downregulate CLU expression, impeding cell migration and invasion while fostering apoptosis in prostate cancer cell cultures." (PMID 38667280, 2024). "Overexpression of CLU promotes tumorigenesis and chemoresistance in multiple cancers like breast and prostate cancer." (PMID 37685987, 2023). "Conversely, promoter demethylation experiments conducted in prostate cancer cells, endothelial cells and retinal pigment epithelial cells using epigenetic drugs significantly increased CLU gene transcription in these cells." (PMID 37685987, 2023). "The downregulation of CLU has also been addressed in another study that investigated the sCLU expression in prostate carcinoma cells." (PMID 37239129, 2023). "Twist is also required for IGF-I-mediated CLU expression and growth signaling in castration-resistant prostate cancer." (PMID 37685987, 2023). "In an in vitro study, it was demonstrated that miRNA-217-5p regulates invasion and migration in prostate cancer by targeting CLU." (PMID 37685987, 2023). "Clusterin expression is reportedly upregulated in many human diseases, including Alzheimer’s, type 2 diabetes and prostate cancer." (PMID 36686470, 2022).
prostate carcinoma (continued). "An increase in concentration of clusterin can be observed inter alia in the course of type 2 diabetes, ischemic heart disease, prostate cancer, and hepatocellular carcinoma (HCC)." (PMID 36071866, 2022). "They identified three stress adaptor proteins: clusterin (CLU), YB-1 and Hsp27 which localize within TNTs formed between prostate cancer cells (PCa)." (PMID 35903550, 2022). "These metabolic stress induced TNT formation in human PC3 and LNCaP prostate cancer cell lines via the stress-induced chaperones clusterin (CLU) and YB-1 (Y-box binding protein-1) and PI3K/Akt activation." (PMID 35267518, 2022). "In HCC and prostate Cancer patients, serum clusterin was significantly elevated, suggesting that serum sCLU is a potential novel serum marker for HCC and prostate Cancer." (PMID 33356806, 2021). "It has been found that CLU mRNA and protein are overexpressed in several human cancers, including cancer of the prostate, breast, lung, kidney, ovary, colon, and endometrial tissues." (PMID 33521130, 2021). "Previous study has proposed controversial functions of CLU in tumorigenesis, e.g., CLU works as a proto-oncogene in prostate cancer and colorectal cancers whereas as a TSG in lung cancer." (PMID 34001209, 2021). "CLU gene transcription and protein expression is upregulated in breast cancer, ovarian cancer, and prostate cancer, and inhibition of CLU expression protects the cell from apoptosis induced by chemotherapy, radiotherapy, and androgen/estrogen depletion." (PMID 33717095, 2021). "Consistent with this, CLU expression was previously found to be significantly reduced in untreated and hormone-refractory human prostate carcinomas." (PMID 33281882, 2020). "al. have previously reported that NK-κB signaling pathway was negatively regulated by CLU in prostate cancer." (PMID 33052230, 2020). "The expression of CLU was previously found to be significantly reduced in untreated and hormone-refractory human prostate carcinomas." (PMID 33281882, 2020). "On the other hand, tumor suppressor function has also been reported for CLU in neuroblastomas 23, prostate cancer 24, and broadly epithelial cancers." (PMID 33052230, 2020). "Clusterin overexpression also upregulates megalin levels (mRNA and protein), which in turn confers clusterin an antiapoptotic role in prostate cancer cells." (PMID 33225275, 2020). "Overexpression of CLU or YB-1 results in increased resistance of cancer cells to taxane, a drug used in the treatment of prostate cancer." (PMID 30872998, 2019). "CLU expression was consistently found to be significantly reduced in both untreated and hormone-refractory human prostate carcinomas, supporting the idea that prostate cell transformation at early stages requires CLU silencing through chromatin remodeling." (PMID 29286311, 2017). "Another recent study demonstrated that HMGB1 released from dying cells induced secretory/cytoplasmic clusterin in prostate cancer cells." (PMID 26925422, 2016). "Recent studies indicated that clusterin gene expressed in kinds of human tumor cells, including liver cancer cells, prostate cancer cells, colon cancer cells and bladder cancer cells." (PMID 26293319, 2015). "It has been reported that CLU overexpression can enhance metastatic potential in prostate cancer, renal cell carcinoma, and breast cancer." (PMID 25609201, 2015). "More evidence suggests that clusterin enhance the resistance to cytotoxic chemotherapy and radiotherapy in breast cancer, lung cancer, cervical cancer, and prostate cancer." (PMID 26293319, 2015). "Studies with lung and prostate cancer cells suggested that an EMT-like process is involved in the CLU-mediated tumorigenic and metastatic processes." (PMID 26399194, 2015). "Custirsen is known as a second-generation antisense oligonucleotide that is complementary to clusterin mRNA and potently suppresses clusterin expression in preclinical models of prostate cancer as well as in clinical trials." (PMID 24772169, 2014).
prostate carcinoma (continued). "Here, we show that diverse anticancer treatments coincidently induce CLU and autophagy, and CLU silencing in prostate cancer cell lines significantly inhibited stress-induced autophagy and enhanced cell death." (PMID 25503391, 2014). "The inactivation of clusterin by anti-sense technology improved the outcomes of radiation therapy for prostate cancer patients." (PMID 24886405, 2014). "In this study, we set out to evaluate the role of CLU in this heat shock response in OS since CLU is dramatically induced by ZOL treatment and CLU inhibitor is currently in phase III clinical Trial in prostate cancer." (PMID 25138053, 2014). "All These data suggest a feed-forward regulation of HSF1 by CLU as we previously reported in prostate cancer." (PMID 25138053, 2014). "Stress-induced autophagy is attenuated with CLU silencing in CLU−/− mice and human prostate cancer cells." (PMID 25503391, 2014). "In prostate cancer the secreted form of clusterin (sCLU) has been described as an anti-apoptotic protein whose expression is increased after therapeutic intervention, whereas, the nuclear protein form nCLU was reported to have pro-apoptotic properties." (PMID 23418433, 2013). "Increase in secreted clusterin levels, triggered via the PI3K pathway activation, was associated with chemoresistance of prostate cancer cells." (PMID 22545109, 2012). "Clusterin expression is enhanced in human prostate cancer, and antisense oligonucleotides targeting clusterin inhibit prostate tumorigenesis." (PMID 21464964, 2011). "In contrast, intracellular clusterin was also shown to inhibit prostate cancer cell proliferation, and clusterin knockout induced highly aggressive transgenic mouse prostate tumors." (PMID 21464964, 2011). "Elevated clusterin expression generally correlates with tumor grade in prostate cancer, although at least one report has shown that the level of clusterin mRNA in prostate cancer is lower than in paired benign tissue from the organ." (PMID 20307318, 2010). "We now describe the production of stable clones of both SV40 immortalised normal prostate epithelial cells (PNT1a) and bone metastatic cells from prostate cancer (PC-3), which can overexpress clusterin." (PMID 15494717, 2004). "Expression of the castration-induced clusterin protein is incompatible with the survival of human prostate cancer cells in tissues and in cell culture." (PMID 15494717, 2004). "Likewise, a direct interaction between miR-195-5p and Clusterin (CLU) is reported in prostate cancer cells through luciferase reporter assay." (PMID 39095857, 2024). "Furthermore, it was shown that CLU expression is necessary for TGFβ-induced cell migration as knockdown of both CLU, and its transcriptional regulator Twist1, significantly reduced the number of invasive prostate cancer cells." (PMID 38319453, 2024). "Additionally, studies on prostate cancer have demonstrated that miRNA-217-5p exerts control over the processes of invasion and migration by specifically targeting CLU." (PMID 38667280, 2024). "The dysregulated expression of CLU and its correlation with tumorigenesis, along with potential clinical implications, have been extensively documented in multiple types of cancer, including lung cancer, prostate cancer, and breast cancer." (PMID 37239129, 2023). "Similarly, YB-1 (Y-box binding protein-1) (in response to endoplasmic reticulum stress) and HIF-1a (produced after exposure to hypoxia-mimetics) directly binds the CLU promoter in prostate cancer cells to stably regulate CLU expression." (PMID 37685987, 2023). "CLU expression has been correlated with metastasis in different types of cancers such as nasopharyngeal carcinoma, breast cancer, hepatocellular carcinoma, colon cancer and prostate cancer." (PMID 37685987, 2023). "Moreover, UBE3A acts as an oncogenic protein that directly regulates the protein stability of p27 and clusterin in prostate cancer." (PMID 35368029, 2022).